DUSP6 (dual specificity phosphatase 6)
Diseases named in the same sentence as DUSP6 in open-access papers (continued):
Sharing a sentence is not in itself a finding about the gene and the disease.
tumor (continued). "Additionally, higher expression of DUSP6 in tumour tissue correlated with HCC recurrence after resection." (PMID 40943262, 2025). "During hypoxia, a hallmark of tumor growth in the tumor environment, hypoxia-induced factor (HIF)-1α upregulates DUSP6 mRNA expression 47, showing that post-transcriptional regulation is a key process in the control of DUSP6 expression." (PMID 41210685, 2025). "Additionally, DUSP6 has shown significant up‐regulation and tumor‐promoting properties in GBM, while FKBP9 has been implicated in fostering the malignant behavior of GBM cells and conferring resistance to endoplasmic reticulum stress inducers." (PMID 40052358, 2025). "Furthermore, its expression rises with tumor malignancy increases, and patient prognosis is negatively correlated with DUSP6 expression level." (PMID 40936711, 2025). "Collectively, these findings indicate that DUSP6 is enriched in this tumor phenotype." (PMID 41028058, 2025). "The pharmacological inhibition of DUSP6 with BCI suppressed tumor migration and invasion." (PMID 40362381, 2025). "In the present study, we explored the association between OCT4 and DUSP6 expression in NSCLC and investigated whether OCT4 exacerbated tumor malignancy and metastasis by directly upregulating DUSP6 expression." (PMID 41210685, 2025). "Our current hypothesis is that DUSP6 suppression might allow tumor initiation, while its expression is required for metastatic cells to re-establish in a new environment." (PMID 41028058, 2025). "Conversely, DUSP6 may also function as a tumour-supporting protein by helping tumour cells to adapt to an abnormally enhanced ERK signalling." (PMID 40943262, 2025). "Indeed, our analysis revealed that DUSP6 was significantly upregulated in tumor cells compared to stromal cells (P < 0.0001)." (PMID 41028058, 2025). "Accordingly, we assessed whether DUSP6 overexpression was localized to specific cell types within the tumor." (PMID 41028058, 2025). "Finally, as for malignant peripheral nerve sheath tumours (MPNSTs), knock down (KD) of DUSP1 and/or DUSP6, which are highly expressed in these tumours as compared to normal tissue, leads to reduced MPNST cell growth and to increased ERK1/2 phosphorylation." (PMID 40943262, 2025). "In recent years, roles of DUSP6 in tumor development are being gradually discovered." (PMID 40936711, 2025). "To investigate the role of DUSP6 in metastasis, we first confirmed its expression in tumor samples." (PMID 41028058, 2025). "This underscored the dual and tissue-specific functions of DUSP6, whose contribution to chemoresistance may vary across different tumour types." (PMID 40943262, 2025). "Moreover, high DUSP6 expression was associated with the level of ERK1/2 expression and with high-risk biological features, including tumour size." (PMID 40943262, 2025). "M62I mutation of DUSP6 was identified in all three osimertinib-resistant PDX tumors, while T846A, N850S, or I931T mutation of RASA1 was detected in at least one osimertinib-resistant PDX tumor." (PMID 39528952, 2024). "Since in the present study acidosis reduced the DUSP6 expression in both tumor lines, it might be possible that the acidosis effect on mitochondrial structure (and by this on OCR) was mediated by the DRP1 phosphorylation status." (PMID 38631214, 2024). "Consistent with the dose-dependent and prolonged exposure in xenograft tumors, oral administration of RMC-6236 led to dose-dependent and durable suppression of RAS pathway signaling as measured by human DUSP6 (a RAS/MAPK pathway transcriptional target) mRNA expression levels in tumor lysates." (PMID 38593348, 2024). "In both tumor lines, DUSP6 expression at mRNA level was significantly reduced after 3 h at pH 6.6." (PMID 38631214, 2024). "The favorable toxicity profile of BCI, its selectivity for DUSP1 and DUSP6, and the ability to inhibit tumor cell proliferation promote further investigation to determine whether this compound targets TAMs and tumor cells." (PMID 38139370, 2023).
tumor (continued). "in agreement with the DUSP6 data, gene set enrichment analysis (GSEA) using the hallmark gene sets revealed that the “KRAS_SIGNALING_UP” gene set was among the significantly enriched sets in primary resistant tumours." (PMID 37604687, 2023). "Some studies have provided evidence that BCI has yielded favorable outcomes when employed on various types of tumor cells through the DUSP6-dependent pathway, while others suggested that the anticancer activity may not result from DUSP6 inhibition." (PMID 37760412, 2023). "Furthermore, our analysis of PDAC tumor specimens demonstrated that high ARF6 level is correlated with low DUSP6 level." (PMID 36017891, 2022). "We came to the conclusion that since DUSP6 serves as a tumor suppressor in ccRCC, its overexpression may be to blame for the suppression of cancer cell migration and EMT brought on by SKA1 deficiency." (PMID 36462498, 2022). "In the human pancreas, DUSP6 expression initially increases in early stage lesions, but is then epigenetically silenced with the lowest levels of DUSP6 found in poorly differentiated and invasive tumours." (PMID 35418690, 2022). "DUSP1 and DUSP6 both exhibit tumor suppressor and tumor promoter activity in different cancers, and the same phosphatases may exhibit opposite roles in different tumors." (PMID 36589747, 2022). "Consistent with the FGF19/FGFR4 downstream pathway, tumor PD assessed by RNAseq revealed an upregulation of CYP7A1 transcript concomitant with downregulation of the MAPK target gene DUSP6, in most on-treatment biopsies obtained at C1D8 with respect to the matched pretreatment sample." (PMID 35655320, 2022). "In addition, the tumor volumes in excised lungs were significantly lower in mice injected with DUSP6‐knockdown cells compared to the sh‐Control cells." (PMID 32159851, 2020). "The development of recurrence and the short PFS and OS in the high‐DUSP6‐expression group among patients with metastasis who were treated with adjuvant chemotherapy may be attributed to the tumor microenvironment." (PMID 32159851, 2020). "The role of DUSP6 in tumor formation depends on the micro-environment." (PMID 31986125, 2020). "DUSP6-positive cells were enriched in surviving tumor cells, which may indicate a role in resistance to chemotherapy or immunotherapy." (PMID 31238530, 2019). "Thus, DUSP6 overexpression in primary and long-term cultures of human GB enhances tumor growth and increases resistance to cisplatin-mediated cell death in vitro and in vivo." (PMID 31018603, 2019). "On the contrary, DUSP6 has been reported as a tumor-promoting factor in human GB." (PMID 31018603, 2019). "Since IL-2 stimulates cytotoxic T cell expansion and activation as well as that of immune suppressive regulatory T cells, it remains to be determined how the IL-2 responsiveness of DUSP6 plays into its apparent effect on immune suppression, and how this relates to tumor immune response." (PMID 30941033, 2019). "Importantly, nuclear DUSP6 was also observed in brain metastases but not lung or pleura metastases from metastatic TNBC patients, while DUSP6 was always cytoplasmic in the primary tumor tissue." (PMID 31238530, 2019). "DUSP6 nuclear expression increases in tumor cells that have transformed into CSCs via EMT." (PMID 31238530, 2019). "In summary DUSP6 is a tumor suppressor in NSCLC and re-establishment of its expression may be a potential strategy to revert poor outcome in NSCLC patients." (PMID 31027181, 2019). "In pancreatic and lung cancer, DUSP6 is considered a tumor suppressor." (PMID 31164954, 2019). "In addition, the tumor suppressive effects of DUSP6 have been demonstrated both in in vivo and in vitro assays, in ESCC and NPC." (PMID 31027181, 2019). "Although much remains unknown regarding the specific effects of DUSP6 on cancer progression and tumor immunity, our findings begin to reveal some novel insights." (PMID 30941033, 2019). "DUSP6 has differing effects on tumor progression depending on the tumor type." (PMID 31164954, 2019).
tumor (continued). "This is also supported by the previous reports of DUSP6 with tumor suppressive roles." (PMID 29352142, 2018). "Overexpression of Dusp6 suppresses tumor cell proliferation." (PMID 30275866, 2018). "We and others found that DUSPs are some of the most robustly regulated downstream targets of EGFR/ErbB2 signaling and indeed both DUSP4 and DUSP6 independently serve key modulatory functions and might be candidate tumor suppressor genes." (PMID 29861842, 2018). "However, it should be noted that most studies into DUSP6 regulation have been carried out in exogenous overexpression systems, cell lines overexpressing the phosphatase or tumor cells." (PMID 29375309, 2017). "The role of DUSP6 as a tumor suppressor or potential oncogene is tissue specific." (PMID 29100381, 2017). "However, we cannot formally exclude the possibility that DUSP5 and DUSP6 regulate tumor cell migration and invasion independently of ERK." (PMID 28910386, 2017). "Clearly, mouse models of Ras and Braf-induced cancers coupled with DUSP6 gene knockout and a more rigorous assessment of DUSP6/MKP-3 levels in larger cohorts of human tumours will be instrumental in clarifying the possible role of DUSP6/MKP-3 as a tumour suppressor." (PMID 26791049, 2016). "In total, 68.4% (13/19) of the tumor biopsies expressed lower levels of DUSP6 than their corresponding normal counterparts; and 36.8% (7/19) of the tumor biopsies displayed at least two-fold downregulation of DUSP6 compared with their paired normal counterparts." (PMID 24260056, 2013). "Accumulating studies have demonstrated that DUSP6 is involved in tumor progression and resistance." (PMID 24260056, 2013). "Another possible mechanism that might activate ERK is through loss of dual-specificity phosphatase 6 (DUSP6), which has also been found in NPC cells and shown to induce tumor formation and metastasis in vivo." (PMID 22500174, 2012). "Obviouosly, depending on the context, DUSP6 affects tumor biology in very different ways." (PMID 22784513, 2012). "Furthermore, it emerged that DUSP6 could be used as a marker for the detection of some tumours, and it can also be used as a target for the treatment of others." (PMID 40943262, 2025). "The concept of ERK activity fitness zone and its feedback control by DUSP6 might help to explain somewhat conflicting observations concerning the role of this phosphatase in cancer, where in some cellular contexts, DUSP6 behaves as an oncogene while in others, it seems to act as a tumor suppressor." (PMID 39436655, 2024). "Therefore, DUSP6 is considered as a potential tumor suppressor." (PMID 39528952, 2024). "However, at the same time, it might be envisioned that DUSP4 and DUSP6 maintain pERK at tolerable levels allowing the tumour cells to reach a state of stemness to overcome proliferative insufficiency." (PMID 37946160, 2023). "Indeed, by immunohistochemistry, we could confirm an enhanced cytoplasmic positivity for DUSP6 in NRAS-induced tumours." (PMID 37946160, 2023). "In addition, two factors of RAS signaling pathways, GRB2 and DUSP6, may be involved in the invasiveness of circulating tumor cells through intricate interactions with the suppressor gene EXT2." (PMID 36672653, 2023). "Whether DUSP4 and DUSP6 serve as oncogenes or tumour suppressors is still under debate." (PMID 37946160, 2023). "Given the evidence that the RAS/ERK signalling pathway is a critical mediator of both tumour initiation and maintenance in the pancreas future work should also concentrate on the identification of the critical ERK-dependent targets that are affected by loss of either DUSP5 or DUSP6." (PMID 35418690, 2022). "Therefore, we further validated the function of DUSP6 in tumor proliferation." (PMID 36017891, 2022).
tumor (continued). "BCI hydrochloride (BCI), a selective dual-specificity phosphatase 6 (DUSP6) inhibitor, is associated with multiple cellular functions, including inhibiting tumor growth and macrophage inflammation; however, its role in regulating osteoclast differentiation remains unknown." (PMID 34803714, 2021). "However, expression of DUSP6 increases as tumor proliferating activity decreases." (PMID 32231719, 2020). "Thus DUSP6 expression is initially elevated and then epigenetically silenced during the progression of mutant Kras-driven pancreatic ductal adenocarcinoma, with the lowest levels detected in the most invasive and poorly differentiated tumours." (PMID 30401534, 2019). "While DUSP6 expression is enhanced in some kinds of cancer (melanoma and glioma cells), suggesting it may be a tumor promotor, its expression is dampened in other tumors where it may exert a role as a tumor suppressor, such as pancreatic invasive cancer, primary lung cancer and ovarian cancer." (PMID 29375309, 2017). "Notably, DUSP6 has a contrary effect in certain other tumor types." (PMID 24260056, 2013). "Another study performed in HCC showed that DUSP6 expression and ERK1/2 phosphorylation were higher in tumour samples compared to peritumoural and normal tissue, as determined by IHC." (PMID 40943262, 2025). "snRNA‐seq analysis revealed that among DUSP4, DUSP6 and ETV4, only DUSP4 was exclusively expressed by cancer cells, making it a more specific biomarker for KC1 tumours, highlighting DUSP4 as a more specific biomarker of KC1 tumours." (PMID 41025426, 2025). "Conversely, DUSP6 has tumor-promoting properties in GBM, as evidenced by the transcriptional up-regulation of DUSP6 in primary and long-term cultures of GBM." (PMID 41029387, 2025). "In PDX JH-2–002, the combination significantly repressed tumor mitotic activity and proliferation as indicated by mitotic counts and Ki-67 decrease and markedly inhibited p-ERK, DUSP6 and several other downstream effectors (p-RSK, p-S6, p-RB, Cyclin D1)." (PMID 41023593, 2025). "Overexpression of DUSP6 in ESCC (SLMT-1, KYSE70, and KYSE450) and NPC cell lines (HONE1, HNE1, CNE2, and SUNE1) reduced tumour growth and invasiveness in vitro and in xenografts in mice." (PMID 40943262, 2025). "During tumour progression, the RAS–RAF–MEK1/2–ERK1/2 pathway was consistently activated, along with upregulation of DUSP4, DUSP6, and the cancer stem cell marker CD133." (PMID 40943262, 2025). "The dramatic combinatorial activity of DUSP6 and HER2 targeting on cellular viability was also evidenced by lack of cytoplasmic eosin staining of the MDA-MB-453 xenograft tumor after 24 d of treatment." (PMID 38886591, 2024). "To further elucidate the activation status of the MAPK-ERK signaling pathway and the expression level of DUSP6 in osimertinib-sensitive and -resistant PDX tumors, we conducted WB analysis on PDX tumors and primary tumor cells isolated from PDX tumors." (PMID 39528952, 2024). "The inhibition of DUSP6 reduced HER3 expression, decreasing tumor lethality and tumor growth in brain metastasis models." (PMID 39769140, 2024). "Treatment of KPARG12C tumours with RMC-4998 and RMC-4550 for 2 days resulted in decreased expression of Dusp6 which indicated suppression of MAPK pathway, consistent with our in vitro observations." (PMID 39322643, 2024). "We measured the response of tumour cells to treatment with a single dose of 10, 25 or 50 mg kg−1 RMC-7977 using quantitative PCR with reverse transcription (RT–qPCR) for human DUSP6, a RAS–MAPK pathway transcriptional target." (PMID 38588697, 2024).
tumor (continued). "The tumour suppressor markers early growth response 1 (EGR1) and dual specificity phosphatase 6 (DUSP6) were downregulated by ∼2-fold in the presence of a bone stroma compared to a fibroblast stroma (p < 0.005)." (PMID 38226014, 2024). "DUSP6 research emphasizes the need for tight control over the DUSP6/ERK1/2 axis to prevent hyperactivity-related toxicity and support tumor cell functions." (PMID 38877005, 2024). "Consistently, ulixertinib-treated PDX tumours displayed increased HER2 and p-ERK1/2, and decreased DUSP4 and DUSP6 IHC staining." (PMID 38509064, 2024). "We next examined the degree of MAPK pathway inhibition after treatment in tumor cells using an MAPK gene expression signature score based on changes in the MAPK-regulated transcripts (DUSP6, ETV4, ETV5 and SPRY4) in tumor epithelial cells." (PMID 36702949, 2023). "Consistently, researchers have reported that the upregulation of DUSP6 plays a tumor-promoting role in GBM, and DUSP6 inhibition increases the radiosensitivity of GBM by regulating DNA damage repair." (PMID 36814929, 2023). "Upon primary or SR development, we observed in all but one tumour a relative increase in ERK phosphorylation levels and DUSP6 expression." (PMID 37604687, 2023). "PICSAR is expressed preferentially in cSCC tumor cells and promotes ERK1/2 activation by downregulating dual specificity phosphatase 6 (DUSP6) promoting cell migration through regulation of integrin expression." (PMID 35408839, 2022). "In conclusion, our results confirm a tumour suppressor role for both DUSP5 and DUSP6 in a clinically relevant model of mutant KRAS-driven oncogenesis." (PMID 35418690, 2022). "In BRAF or RAS mutant tumor cells, DUSP4, DUSP6, SPRY2, and SPRY4 tend to be highly expressed, allowing tumors to evade regular MAPK signaling pathway feedback." (PMID 36437939, 2022). "We injected shRNA‐mediated DUSP6‐knockdown Hec1 cells at different inoculation densities into 6‐week‐old female NOD/SCID mice and observed tumor formation 8 weeks later." (PMID 32159851, 2020). "In surviving 4T1 tumor cells in Abraxane or anti-PD1-treated mice, nuclear DUSP6 was enriched in both triple-positive cells (CSV+ABCB5+DUSP6+) and the double-positive ABCB5+DUSP6+ tumor cell pool." (PMID 31238530, 2019). "DUSP6/MKP3 is a dual-specific phosphatase that regulates extracellular regulated kinase ERK1/2 and ERK5 activity, with an increasingly recognized role as tumor suppressor." (PMID 31027181, 2019). "We further assessed the impact of DUSP6 expression on allogeneic GVHD and graft-versus-tumor (GVT) effects using an allogeneic mouse model." (PMID 29765028, 2018). "After 20 days, tumours treated with BRAF inhibitor alone had resumed growth, whereas ERK activity was still moderately inhibited as seen by the reduced expression of DUSP6." (PMID 28606996, 2017). "For example, some DUSPs exhibit loss of heterozygosity in some cancers with additional functional studies supporting potential roles as tumor suppressors, including DUSP4, DUSP6 and DUSP7." (PMID 25568665, 2014). "Using Spearman’s rank correlation analysis, DUSP6 expression was observed to be negatively correlated to pathological grade, indicating that DUSP6 is important in human ESCC carcinogenesis, particularly in tumor progression and differentiation." (PMID 24260056, 2013). "DUSP6 and RGS16 (regulator of G-protein signaling 16) transcriptional upregulation inhibits tumor cell proliferation and ERK phosphorylation and serves as a negative regulatory mechanism to prevent further ERK phosphorylation." (PMID 19636436, 2009). "DUSP6 and RGS16 transcriptional upregulation inhibits tumour cell proliferation and ERK phosphorylation, and serves as a negative regulatory mechanism to prevent further ERK phosphorylation." (PMID 16012519, 2005).